EMP1 (epithelial membrane protein 1)
Diseases named in the same sentence as EMP1 in open-access papers (continued):
Sharing a sentence is not in itself a finding about the gene and the disease.
tumor (continued). "However, the possible role of Fhit, CD226, and Emp1 as tumor suppressors in CD8+ Dnmt3aΔ/Δ PTCL is unclear." (PMID 27690235, 2016). "EMP-1 promoted tumor growth of PC9 cells was also observed in vivo in a nude mouse xenograft model." (PMID 26472188, 2015). "We found that PIGR, LPRP, PLUNC, and EMP1 are downregulated in almost all the tumours." (PMID 14612907, 2003). "Finally, in vivo experiments confirmed that EMP1 promotes tumor growth and cisplatin resistance." (PMID 36708070, 2023). "Unlike other cancer types, EMP1 has been implicated in CRC as a putative tumor suppressor, which may inhibit cell migration and promote apoptosis." (PMID 37679762, 2023). "VARGG accurately reveals the spatial organization of tumors and identifies key genes related to tumor progression and immune microenvironment (VEGFA, CD74, SPP1, IGFBP5, TIMP2, EMP1, THY1)." (PMID 41275376, 2025). "In contrast, EMP1 and EMP3 expression levels in the Tumor group were only marginally higher than those in the Normal group, and these differences were not statistically significant (p > 0.05)." (PMID 39866225, 2025). "To understand the role of EMP1 in CAF infiltration in TNBC, we first established a CAF cell line from a TNBC patient who has underwent tumor resection surgery and cell co-cultured the cells with TNBC cell lines." (PMID 40016223, 2025). "To further evaluate the biological effects of EMP1 on CAF infiltration in vivo, we resuspended TNBC cells and CAFs at a 5:1 ratio and injected the cells into a nude mouse xenograft tumor model." (PMID 40016223, 2025). "We identified its downstream effector genes, EMP1 and AUTS2, which play crucial roles in mediating its tumor-suppressing effects." (PMID 37679762, 2023). "Furthermore, the increased protein level of VEGFC and BCL2 as well as reduced cell apoptosis caused by depletion of UTX could be rescued by ectopic expression of EMP1, suggesting that EMP1 is a significant effector gene mediating the tumor-suppressing function of UTX in CRC." (PMID 37679762, 2023). "Among these gene/subgroup combinations, there was increased expression of EMP1 and FGFR1 in tumor cells compared to other cells in c9 fibroblasts." (PMID 38187400, 2023). "Meanwhile, EDNRA, PRRX1, EMP1, AKR1B1, and SULF2 exerted an important role in cancer progression in other tumor types." (PMID 36816947, 2023). "In ovarian cancer, EMP1 overexpression can activate the Ras/Raf/MAPK/c-Jun signaling pathway and promote tumor cell proliferation, invasion, and EMT." (PMID 36217151, 2022). "Of note, LAMC2 has been previously identified as a specific marker for tumor budding in multiple tumor types, including CRC18, and we confirmed that its expression correlated with EMP1 mRNA in CRC patient samples." (PMID 36352230, 2022). "Fitting the scRNAseq analyses, we identified two Emp1-TOM+ subsets; one expressed KRT20 and was located mainly in the tumor cores, whereas the other was positioned at invasion fronts, lacked KRT20 and expressed the highest levels of TOM reporter." (PMID 36352230, 2022). "The mRNA expression levels of AHNAK, EMP1, RASGRP4, and HSPA1L were significantly down-regulated in BUC tumor tissues compared with normal tissues while SLC1A6 and PRSS8 were significantly up-regulated (P < 0.05)." (PMID 34905506, 2021). "Multivariate Cox regression analysis in the TCGA-BLCA dataset revealed that the expression levels of EMP1, RASGRP4, AHNAK, SLC1A6, and PRSS8 in tumor tissues were independent predictors for the unfavorable prognosis of BUC patients." (PMID 34905506, 2021).
tumor (continued). "We identified six survival-related genes, EMP1, TPM1, NRP2, FGFR1, CAVIN1, and LATS2, found in the DEG analyses of both, tumor-paracancerous and paracancerous-normal differentially expressed data sets." (PMID 32695477, 2020). "Among them, only EMP1, PTPRG and DDX17 were downregulated in LUAD tissues by the analysis of TCGA database, suggesting their tumour suppression role." (PMID 31012177, 2019). "We found in this study that the expression of epithelial membrane protein 1 (EMP1) was highly induced in cancer cells, and subsequently investigated its role in tumor metastasis." (PMID 29867202, 2018). "Some of these genes, such as KRT19, EMP1, and PARP2, have evidence from previous studies, which indicate their higher expression levels in the original tumors compared with PDX tumor cells." (PMID 29534550, 2018). "Moreover, both ARHGAP18 and EMP1 might work as tumour suppressors." (PMID 23119007, 2012). "The role of epithelial membrane protein 1 (EMP1) in tumor microenvironment (TME) remodeling has not yet been elucidated." (PMID 40016223, 2025). "Subclusters 4 and 5 may be related to tumor invasion and metastasis (migration factors CXCL3 and CXCL1; adhesion factors CEACAM6 and EMP1), suggesting that they may be tumor cell clusters with a greater degree of malignancy." (PMID 38927691, 2024). "In this study, we found that the LAMC2-expressed cells and EMP1-expressed cells may be the same cell subset named EP1, which initiates tumor metastasis." (PMID 38818308, 2024). "Lgr5-EGFP fluorescence was absent in disseminated tumor cells (DTCs) and micrometastases, but was progressively gained during metastatic outgrowth, in a marked antithetic pattern to Emp1-TOM expression." (PMID 36352230, 2022). "Furthermore, it was evident an arrangement of tumor cell types reminiscent of the in vivo organization; Lgr5-EGFP cells were positioned at the organoid center, whereas Emp1-TOM+ cells relocated to the boundaries in contact with the fibroblast population." (PMID 36352230, 2022). "Expression data of EMP1, EMP2, EMP3 and PMP22 were obtained from all tumor samples." (PMID 21159173, 2010). "Thirdly, due to time constraints, the subcutaneous tumor formation experiment in animals only included an overexpression group to verify whether EMP1 exerts tumor-suppressing effects, without establishing a knockdown group for further validation." (PMID 41458590, 2025). "To further examine the mechanistic role of EMP1 in tumor metastasis, we generated clones of FLAG-EMP1-LNCaP cells and selected two of these clones: LNCaP #2 cells, which faintly expressed FLAG-EMP1, and LNCaP #17 cells, which expressed high levels of FLAG-EMP1." (PMID 29867202, 2018). "Knockdown of MAML2 significantly affected cell colony formation in vitro, the knockdown of EMP1, IRS2, and SP100 did not affect tumor growth or metastasis." (PMID 40781158, 2025).
cancer (49 papers, 2007 to 2025). A tumor composed of atypical neoplastic, often pleomorphic cells that invade other tissues. "High EMP1 expression in these cancers is often associated with advanced stage and poor overall survival." (PMID 41465326, 2025). "Infiltration analysis and immunohistochemical (IHC) staining of serial sections confirmed the critical role of EMP1 in cancer-associated fibroblast (CAF) infiltration." (PMID 40016223, 2025). "EMP1 (Epithelial Membrane Protein1) has been implicated in various cancer types and is regarded to promote cancer progression by modulating cell growth and metastasis." (PMID 37679762, 2023). "The reduced expression of EMP1 has been reported to be associated with poor prognosis in patients with certain types of malignant tumors and regarded as an independent predictor of poor survival in various solid tumors." (PMID 35432717, 2022). "Dysregulation of EMP1 expression is linked to epithelial diseases, particularly human cancers." (PMID 37547756, 2023). "EMP1 exhibits paradoxical roles in tumorigenesis and cancer progression, manifesting not only across diverse malignancies but also in distinct cellular behaviors." (PMID 41458590, 2025). "Existing studies have shown that Epithelial membrane protein 1 (EMP1) is abnormally expressed in a variety of cancers and is closely related to the occurrence and development of tumors." (PMID 41458590, 2025). "EMP1, a member of epithelial membrane proteins (EMPs) family, plays an important role in cancer invasion and metastasis." (PMID 38341586, 2024). "Ascore comprises four genes (CERCAM, EMP1, GNLY, and PTPRR), which have been previously reported to be strongly associated with cancer." (PMID 38341586, 2024). "EMP1 expression increased as the cancer stage progressed, and therefore, we focused on the EMP1 gene." (PMID 36708070, 2023). "Extensive research has been conducted into the role of EMP1 in pathogenesis and tumorigenesis of various cancer." (PMID 37008256, 2023). "EMP1 belongs to the epithelial membrane protein family, and its functions vary depending on distinct cancer contexts." (PMID 37386026, 2023). "In the future, more validation methods should be performed to verify the importance of these EMP1+/COL3A1+ fibroblasts during the BoM process in more types of cancers." (PMID 38187400, 2023). "Previous research revealed that EMP1 plays a role in proliferation, migration, metastasis, and tumorigeneses in different cancers via a variety of mechanisms." (PMID 37008256, 2023). "Previous studies found that EMP1 regulates cancer cell migration and proliferation, and we suspect it has a similar role in activated HSCs." (PMID 37008256, 2023). "The GSEA KEGG analysis found that the genes enriched in the high EMP1 expression group were mainly associated with focal adhesion, the PI3K‐Akt signaling pathway, and proteoglycans in cancer, as well as cell adhesion molecules." (PMID 36708070, 2023). "In this study, we first utilized the public databases to investigate the expression of EMP1 in HNSCC and the results showed that EMP1 was expressed at low levels in cancer." (PMID 35432717, 2022). "A previous study has corroborated that EMP1 serves as a promising oncogene and is obviously downregulated in tumors and can enhance cell cytotoxicity in various cancer cells." (PMID 35432717, 2022). "Herein, we mainly summarized the structure, mutation, and modification sites of PMP22, EMP1, EMP2, and EMP3, as well as the diseases related to these proteins, especially cancer types." (PMID 36217151, 2022). "Some BIIGs were upregulated in multiple cancer types: Top2a, Mki67, Rrm2, Mcm6, and Spp1 were upregulated in more than eight cancer types, while Emp1, Ptx3, and Socs3 were upregulated in seven cancer types." (PMID 36605216, 2022). "EMP1 can regulate cell proliferation and differentiation, especially in epithelial cells and various malignant tumors." (PMID 36217151, 2022).
cancer (continued). "Some BIIGs were downregulated in various cancers, especially Il1r1, Srgn, Emp1, Ptx3, Socs3, and Cebpd, which were downregulated in at least seven cancer types." (PMID 36605216, 2022). "Of the 25 immune-related genes, 24 genes (96%) demonstrated higher expression levels in NOTCH4-Mut tumors compared with wildtype ones, but one gene (4%), EMP1, showed decreased expression, implying a potential decrease in cancer invasiveness and metastasis." (PMID 35967450, 2022). "EMP1 has been proposed as a marker for resistance in cancer therapies and related to poor prognosis." (PMID 33995625, 2021). "On top of that, the up-regulation of EMP1 was shown to increase cancer cell migration and lead to metastasis." (PMID 33995625, 2021). "We have recently demonstrated that the upregulation of EMP1 expression facilitates cancer cell migration and invasion through the activation of a small GTPase, Rac1." (PMID 31652725, 2019). "Further we have found that copine-III binds to EMP1, which enhances signal transduction to influence the invasiveness of cancer cells." (PMID 31652725, 2019). "The reason for the opposing activities of EMP1 in cancer progression in these types of cancer should be determined in the future." (PMID 31652725, 2019). "In this context, we highlight in this review the functional aspects of the EMP family members EMP1, EMP2, and EMP3 related to their pathophysiology, particularly where associated with cancer metastasis." (PMID 31652725, 2019). "Further, the exact mechanism of EMP1-mediated signal transduction pathways in the regulation of cancer metastasis is largely unanswered." (PMID 31652725, 2019). "The direct binding of copine-III to the intracellular region of EMP1 is critically involved in cancer invasion." (PMID 31652725, 2019). "In an animal model, EMP1 significantly enhances the migration of cancer cells and the formation of metastatic lesions in the lymph nodes, lungs, or both." (PMID 31652725, 2019). "The validation of decreased FOSL1 (Fos-like antigen 1) and increased EMP1 was further define the potential anti-cancer effect of ZNF750." (PMID 29416636, 2018). "To date, immunotherapy based on monoclonal antibodies against cancer cell surface proteins, including those with four transmembrane domains (like EMP1), has been clinically approved and shown to be effective for the treatment of several types of cancer." (PMID 29867202, 2018). "The intracellular loop region of EMP1 also represents a candidate target to inhibit cancer metastasis, because EMP1-induced signal transduction is triggered by the complex formation of EMP1 and copine-III." (PMID 29867202, 2018). "Semi-quantitative PCR analysis revealed that endogenous expression of EMP1 was very low in LNCaP cells compared with other types of cancer cells." (PMID 29867202, 2018). "Among these genes, we selected a cell surface protein EMP1, which contains four transmembrane domains, for further examination, because little is known about the role of this molecule in cancer progression and metastasis." (PMID 29867202, 2018). "Furthermore, EMP1 is a biomarker in gefitinib‐resistant cancers, suggesting its role in the regulation of drug resistance development." (PMID 36708070, 2023). "Finally, a strong correlation was discovered between EMP1/COL3A1 genes and EMT-featured gene pan-cancer-wide, implying a possible underlying mechanism through an EMT perspective." (PMID 38187400, 2023). "Furthermore, a series of cell density tests elucidated the contribution of TAZ/EMP1 axis in cancer progression." (PMID 35432717, 2022). "Moreover, the epithelial membrane protein 1 (EMP1) was identified to be induced in PCa cells after contact with stroma cells subsequently promoting cancer progression and metastasis formation in the lymph nodes and lung via a Rac1-dependent mechanism." (PMID 33747899, 2020). "In these cancers high endogenous EMP1 expression correlates with poor patients’ outcome." (PMID 31450568, 2019).
cancer (continued). "Further, we successfully explored the mechanism of EMP1-induced cancer metastasis." (PMID 31652725, 2019). "Taken together, this study describes a potential mechanism of cancer metastasis via EMP1 signaling." (PMID 29867202, 2018). "Targeting of EMP1 may have anti-cancer therapeutic potential by inhibiting cancer metastasis to reduce mortality." (PMID 29867202, 2018). "Based on these studies and our findings, targeting of the tetra-spanning membrane proteins, including EMP1, may reduce the malignancy of cancer cells, leading to the development of novel anti-cancer therapeutics." (PMID 29867202, 2018). "Overexpression of EMP1 leads to increased apoptosis via caspase-9, reduced VEGF-C expression, and diminished cancer cell ‘stemness’." (PMID 41465326, 2025). "EMP1 mediates the cell communication between TNBC cells and CAFs by enhancing cancer cell-derived IL6 secretion." (PMID 40016223, 2025). "We identified a metastasis-related cancer cell subset EP1, which was characterized with a high expression of KRT17, LAMC2, EMP1, and PLAC8." (PMID 38818308, 2024). "All the other genes (ATF3, EMP1, GADD45B, SOCS3, and ZFP36), distinct from EGR3, have been independently demonstrated to function as migration inhibitors in cancer cells." (PMID 38543002, 2024). "Metastasis-related cancer cell subset EP1 was characterized by gene expression of KRT17, LAMC2, and EMP1." (PMID 38818308, 2024). "In this study, GSEA KEGG analysis found that the genes enriched in the high EMP1 expression group were mainly involved in focal adhesion, the PI3K‐Akt signaling pathway, proteoglycans in cancer, and cell adhesion molecules." (PMID 36708070, 2023). "More important, this group of genes also included genes whose roles in cancer have yet to be fully addressed (e.g., TM4SF1, TM4SF19, EMP1, PHLDA1, and PHLDA2)." (PMID 35831322, 2022). "EMP1 is a target of c-MYC, and is highly expressed in undifferentiated cells; it has been reported as a negative regulator in some cancers including nasopharyngeal cancer, and breast cancer." (PMID 32857809, 2020). "All six selected survival-related genes (EMP1, TPM1, NRP2, FGFR1, CAVIN1, and LATS2) were reported to play a positive role in disseminating cancer cells or invasion in many kinds of cancers." (PMID 32695477, 2020). "The cancer related category apoptosis was over-represented with both up- and down-regulated genes, represented by two up-regulated genes (TNS3, EMP1) and five genes down-regulated (DNASE1L2, CXCR4, Gal-7, FKBP5, SGK1)." (PMID 25867603, 2015). "Elevated EMP1 inhibits the interference of SMAD7 with SMAD2/3 activity by promoting the binding of VASP to SMAD7, ultimately activating the TGF-β/Smads signaling pathway-induced cancer cell invasiveness." (PMID 41285728, 2025). "EMP1, EMP2, and EMP3 have been reported as novel therapeutic targets in human cancer." (PMID 36936167, 2023). "Enriched EMP1+ fibroblasts were found in BoM samples, and a COL3A1-ADGRG1 communication between these fibroblasts and cancer cells was identified which might facilitate the BoM process." (PMID 38187400, 2023). "Interestingly, through Pearson analysis, we also find a significant correlation between EMP1 and COL3A1 expressions in fibroblasts/osteoblasts among three types of cancer, suggesting a potential connection between these two genes." (PMID 38187400, 2023). "Combining the significantly enriched iron ion binding signal pathway between EMP1-low and high groups, we speculate that maybe there was activated ferroptosis in HNSCC cancer that could induce cell death." (PMID 35432717, 2022). "Expression analysis revealed a different mRNA expression pattern of EMPs with significant downregulation of EMP1 (nine out of ten cell lines) and EMP2 (six out of ten cell lines), but significant upregulation of EMP3 in more than half of the cancer cell lines compared to HBEC." (PMID 33799364, 2021).
cancer (continued). "Considering that EMP1, EMP2, and EMP3 have been reported to play important roles in various malignant tumors, increased expression of EMP1 and EMP3, along with stromal cellularity and stromal atypia, imply that increased EMP expression in PT could suggest a higher malignant potential for PT." (PMID 32857809, 2020). "The research group seems to consider that EMP1 may negatively regulate the progression of ovarian cancer and decrease the severity of the cancer, although the detailed evidence is not provided." (PMID 31652725, 2019). "For example, the nine amino acid peptide (FTMEKGNRF) at the intracellular loop of EMP1, which was used in the identification of copine-III and binds to copine-III, may block the EMP1–copine-III binding and thus limit the effects of EMP1 on cancer metastasis." (PMID 29867202, 2018).